SMAD7 (SMAD family member 7)
Diseases named in the same sentence as SMAD7 in open-access papers (continued):
Sharing a sentence is not in itself a finding about the gene and the disease.
renal fibrosis (continued). "In this regard, rebalancing the disturbed Smad3/Smad7 ratio, through downregulating Smad3 and upregulating Smad7 simultaneously, seems to be an effective strategy for treatment of renal fibrosis." (PMID 25852569, 2015). "The combination of AA and NG produced an additive effect on inhibition of renal fibrosis by blocking Smad3 while upregulating Smad7." (PMID 26474462, 2015). "In the present study, we report here that inhibition of Smad3 with naringenin (NG) and upregulation of Smad7 with asiatic acid (AA) produced an additive effect on inhibition of renal fibrosis in a mouse model of obstructive nephropathy." (PMID 26474462, 2015). "Increasing evidence shows that TGF-β1 is a key mediator in diabetic nephropathy (DN) and induces renal fibrosis positively by Smad3 but negatively by Smad7." (PMID 24646636, 2014). "This indicates that OzoneOP affects the expression of TGF-β1/Smad7 and thereby exerts protective effects against the renal fibrosis induced by IRI." (PMID 25371729, 2014). "In our studies, the KKAy mice that exhibited the down-regulation of Smad7 developed more severe renal dysfunction, which provided further confirmation of the effect of Smad7 disruption on renal fibrosis." (PMID 24885228, 2014). "Evidence for protective role of Smad7 in renal fibrosis comes from studies in which Smad7 gene knockout (KO) mice develop worse fibrosis in obstructed nephropathy." (PMID 23301086, 2013). "The present finding that disrupted Smad7 enhanced Smad3-mediated renal fibrosis added a new evidence for a protective role of Smad7 in ANG II-mediated hypertensive nephropathy." (PMID 23301086, 2013). "An important finding in the present study is that loss of Smad7 promoted ANG II-induced activation of TGF-β/Smad signaling, resulting in a progressive renal fibrosis in a mouse model of hypertension." (PMID 23301086, 2013). "In summary, the current study found that disruption of Smad7 significantly increases Ang-II induced renal fibrosis and inflammation." (PMID 23301086, 2013). "To investigate the mechanisms by which deletion of Smad7 promoted Ang-II induced renal fibrosis and inflammation, we studied TGF-β/Smad and NF-κB signaling pathways in the hypertensive kidney." (PMID 23301086, 2013). "Smad7 is an inhibitory Smad that negatively regulates TGF-β/Smad-mediated renal fibrosis by facilitating degradation of TGF-β receptor-1 and Smads via the Smurf2 and arkadia-dependent ubiquitin-proteasome mechanism." (PMID 23301086, 2013). "It should be pointed out that although Smad7 exerts its protective role in both renal fibrosis and inflammation, role of TGF-β1 under disease conditions is highly diverse due to the complexity of its downstream signaling pathway." (PMID 23301086, 2013). "Researchers have developed and validated AANG—a botanical formulation comprising asiatic acid (a Smad7 activator) and naringenin (a Smad3 inhibitor) that attenuates renal fibrosis and inflammation in DKD through modulation of the TGF-β/Smad3/Smad7 signaling pathway." (PMID 40861214, 2025). "The expression of genes that promote renal fibrosis (Smad2, Smad3, Smad4, Shh, Dll1) was downregulated, while the expression of genes that inhibit renal damage (Smurf1, Smurf2, Smad1, Smad5, Smad6, Smad7) was increased in the WT+miPEP31 group (PEP1/2) compared with the WT+ cPEP (SCR1/2) group." (PMID 38992718, 2024). "Mechanically, we uncovered that treatment with SIS3 inhibited T2DN in db/db mice by inhibiting Smad3 while upregulating Smad7, thereby restoring the balance of Smad3/7 signaling and protecting the kidney from the development of progressive renal fibrosis in db/db mice." (PMID 38164169, 2024). "Consistent with previous studies that found that Smad2,Smad3,Smad4 and Smad7 might be involved in TGF-β1-mediated renal fibrosis, our study observed alterations in the phosphorylation activation of Smad2,Smad3,Smad4 and Smad7 in TGF-β1 treated HK-2 cells." (PMID 38195664, 2024).
renal fibrosis (continued). "Studies have now demonstrated that TGF‐ β1 signalling through type I TGF‐β receptors leads to phosphorylation and nuclear translocation of Smad2 and Smad 3 that promotes renal fibrosis, while the overexpression of Smad7 prevents TGF‐ β1‐mediated renal fibrosis." (PMID 36479618, 2023). "miR-21 plays an important role by targeting PTEN and Smad7 in the progression of renal fibrosis." (PMID 38201260, 2023). "Therapeutically, Smad7 overexpression has shown promise in renal fibrosis models." (PMID 37790634, 2023). "The inactivation of NF-κB signaling mediated by Smad7 might serve as a critical ‘bridge’ that connects the protective effects on renal fibrosis and inflammation that result from treatment with CTRP13." (PMID 38255158, 2023). "On the other hand, SMAD7 inhibition increases renal fibrosis and inflammation, indicating that SMAD7 may be the most crucial regulator for inflammation and renal fibrosis." (PMID 36428551, 2022). "Smad3 can also regulate Smad7 to play a role in renal fibrosis." (PMID 35541902, 2022). "Similarly, SMAD2 and SMAD7 are renoprotective in the course of renal fibrosis, wherein Smurf2 stimulates the degradation of SMAD2, resulting in weakened or repressed biological function." (PMID 35379779, 2022). "A recent experimental study found that latent TGF-β1 may protect the kidney from TGF-β/smad mediated renal fibrosis by inhibiting arkadia-mediated Smad7 ubiquitin degradation." (PMID 35111409, 2022). "Similarly, Pusoon Chun showed that another class IIa HDAC, HDAC4, can increase the expression of multiple profibrotic molecules by inhibiting Smad7 in renal fibrosis." (PMID 36263180, 2022). "Therefore, deletion of Smad3 or overexpression of Smad7 protects kidney from Smad3-mediated renal fibrosis and NFκB-driven renal inflammation under diabetic and hypertensive conditions 3, 7-11." (PMID 36147472, 2022). "The TGF-β signaling pathway was also enriched in the present study, and the expressions of Smad1, Smad6, and Smad7 were significantly upregulated, which might indicate channel catfish renal fibrosis." (PMID 35747138, 2022). "Mechanically, we uncovered that the combinational treatment with AA and NG produced a better effect on rebalancing Smad3/Smad7 signaling in the diabetic kidney, thereby resulting in more effectively inhibiting Smad3-mediated renal fibrosis and NF-κB-driven renal inflammation." (PMID 36147472, 2022). "Erbb4-IR binds to the inhibitory Smad7 and blocks TGF-β/Smad3-induced renal fibrosis, while overexpression of Erbb4-IR may promote fibrosis by downregulating the expression of Smad7." (PMID 34054586, 2021). "Latent TGF-β1 may protect kidneys from TGF-β1/Smad3-mediated renal fibrosis and NF-κB-driven renal inflammation in diabetes through inhibiting Arkadia-mediated Smad7 ubiquitin degradation." (PMID 34512167, 2021). "Therefore, Erbb4-IR functions as a trans-regulator to negatively regulate miR-29b and Smad7 in renal fibrosis." (PMID 34360646, 2021). "It is now clear that Smad7 is an integrated inhibitor not only for inhibiting TGF-β/Smad3-mediated renal fibrosis by competing with the R-Smad binding to the TβRI 24 but also for suppressing IκBα ng NF-κB-driven renal inflammation by inducing, an NF-κB inhibitor 25,26." (PMID 34512167, 2021). "Collectively, the TGF-β/Smad3-mediated lncRNAs may act as anti-fibrotic or pro-fibrotic mediators in the fibrotic process by binding to Smad3, Smad7, or inflammatory molecules to inhibit or enhance renal fibrosis and inflammation." (PMID 34054586, 2021). "It has been reported that miR‐21 can target Smad7 to induce renal fibrosis." (PMID 33733577, 2021). "However, ultrasound microbubble-mediated delivery of Smad7 into the kidney of db/db mice ameliorates the renal fibrosis and inflammation accompanied by improved renal function." (PMID 34360646, 2021).
renal fibrosis (continued). "TGF-β may specifically regulate renal fibrosis and inflammation via downstream Smad-dependent mechanisms involving Smad3, Smad4, Smad7, and particularly Smad3-dependent non-coding RNAs." (PMID 32258028, 2020). "In addition, strategy targeting rebalancing TGF-β/Smad3/Smad7 signaling in vivo has been demonstrated to be effective for reducing renal fibrosis in obstructive nephropathy." (PMID 30524310, 2018). "Thus, rebalancing the TGF-β/Smad signaling pathway through the upregulation of Smad7 and the suppression of Smad2/3 activation are prospective treatment options for renal fibrosis." (PMID 30101622, 2018). "That delivery system significantly over-expressed Smad7 in the kidney and inhibited renal fibrosis." (PMID 30410705, 2017). "Blockade of NF-κB-driven renal inflammation and TGF-β/Smad3-mediated renal fibrosis by preventing the Smurf2-mediated Smad7 degradation pathway may be mechanisms through which TSF inhibits type 2 DN." (PMID 26807792, 2016). "If Smad7 is extensively degraded, Smad3 becomes overactivated and renal fibrosis is enhanced." (PMID 26807792, 2016). "More significantly, we also found that inhibition of Smurf2-mediated ubiquitin degradation of Smad7 may be a central mechanism by which TSF suppressed both TGF-β/Smad3-mediated renal fibrosis and NF-κB-dependent renal inflammation in the diabetic kidney." (PMID 26807792, 2016). "Inhibition of TGF-β/Smad3 and NF-κB signaling pathways may be mechanisms by which Smad7 attenuates AA-induced renal fibrosis and inflammation." (PMID 25883225, 2015). "Therefore, overexpression of Smad7 has been shown to be a therapeutic agent for renal fibrosis in various models of kidney diseases." (PMID 25852569, 2015). "Importantly, we also found that overexpression of Smad7 locally in the kidneys with established chronic AAN was capable of attenuating progressive chronic AAN by inactivating TGF-β/Smad3-medated renal fibrosis and NF-κB-driven renal inflammation." (PMID 25883225, 2015). "Deletion of Smad7 enhances renal fibrosis and inflammation, whereas, overexpression of Smad7 attenuates renal fibrosis and inflammation by blocking the activation of both TGF-β/Smad and nuclear factor-κB (NF-κB) signaling pathway in a variety of animal models with kidney diseases." (PMID 25883225, 2015). "However, opposite results were shown in a kidney disease model of obstructive nephropathy, in which over-expression of Smad7 inhibited the expression of miR-192 and resulted in suppression of renal fibrosis." (PMID 25884636, 2015). "Immunohistochemistry, western blot, and real-time PCR also showed that restored renal Smad7 blocked AA-induced severe renal fibrosis such as upregulation of collagen I and α-SMA and inhibited renal inflammation including F4/80+ macrophages and CD3+ T cells and upregulation of MCP-1 and TNFα." (PMID 25883225, 2015). "Once Smad7 is degraded, activation of Smad3 and renal fibrosis is enhanced." (PMID 24646636, 2014). "Blockade of TGF-β/Smad3-mediated renal fibrosis by downregulating TGF-β1 and microRNA-21 expression, thereby restoring the balance of Smad signaling by upregulating an inhibitory Smad7, resulting in a possible underlying mechanism by which CHYS inhibits diabetic nephropathy associated with fibrosis." (PMID 24646636, 2014). "Enhanced Sp1-TGF-β1/Smad3-NF-κB signaling may be the major mechanistic pathway by which deletion of Smad7 promotes ANG II-mediated renal fibrosis and inflammation." (PMID 23301086, 2013). "The findings that disruption of Smad7 enhanced ANG II-induced renal injury by promoting TGF-β/Smad2/3-mediated renal fibrosis and NF-κB-driven renal inflammation added new information for a better understanding of the mechanism of Smad7 in negatively regulating ANG II-mediated kidney injury." (PMID 23301086, 2013). "In addition to its effect on renal fibrosis, Smad7 has been shown to play a protective role in fibrosis in other organs." (PMID 22204639, 2011).
renal fibrosis (continued). "Consistently, overexpression of Smad7 in diabetic rats could attenuate renal fibrosis and inflammation." (PMID 22204639, 2011). "Consistently, deletion of Smad7 in the mice was found to promote renal fibrosis in UUO kidneys." (PMID 22204639, 2011). "Therefore, Smad7 plays an important role in the pathology of renal fibrosis." (PMID 34059951, 2021). "Therefore, treatments by rebalancing Smad3/Smad7 signaling or by specifically targeting Smad3-dependent non-coding RNAs that regulate renal fibrosis or inflammation could be a better therapeutic approach." (PMID 32258028, 2020). "Thus, rebalancing the TGF-β/Smad signaling by downregulating Smad3 and upregulating Smad7 might be an effective strategy for treatment of renal fibrosis." (PMID 30271345, 2018). "Thus, blockade of TGF-β/Smad3-mediated renal fibrosis could be a mechanism by which Smad7 protects against chronic AAN." (PMID 25883225, 2015). "Thus, the imbalance of TGF-β/Smad signaling may be a major cause of renal fibrosis and rebalancing this pathway by inactivating Smad3 while upregulating Smad7 may produce a better therapeutic effect on renal fibrosis." (PMID 26474462, 2015). "Indeed, loss of renal Smad7 was found in the kidney with chronic AAN, which may account for TGF-β/Smad3-mediated renal fibrosis." (PMID 25883225, 2015). "Moreover, the IRI-associated molecules α-smooth muscle actin (α-SMA), transforming growth factor (TGF)-β1 and Smad7 were tested to determine whether and how OzoneOP affected the renal fibrosis." (PMID 25371729, 2014). "Increasing evidence has indicated that disruption of Smad7 may accelerate renal fibrosis." (PMID 24885228, 2014). "Furthermore, loss of miR-29 may also be a mechanism through which disruption of Smad7 enhances Ang II-mediated renal fibrosis and inflammation." (PMID 23301086, 2013). "Our recent studies also demonstrated that blocking class IIa HDACs with MC1568 increased Smad7 expression and decreased Smad3 expression in a murine model of UUO-induced renal fibrosis." (PMID 41275091, 2025). "Animals with renal fibrosis showed decreased SOD activity and increased expression of TGF-β1, TNF, VEGF, Smad3, and Smad7, which correlated with increased expression of miR-148a-3p." (PMID 40004454, 2025). "Highly expressed EVL binding to Smad7 abrogated the Smad7‐induced suppression of transforming growth factor‐β (TGF‐β1)/Smad3 signal transduction, which conversely facilitated renal fibrosis progression." (PMID 37537731, 2023). "Currently, miR-21 has been reported in several articles and is associated with disease progression in colon cancer, breast cancer, renal fibrosis, cardiac fibrosis by targeting PTEN, PDCD4, SMAD7 and SPRY, and others." (PMID 35897096, 2022). "Our previous studies demonstrated a combination of Traditional Chinese Medicine derived Smad7 agonist Asiatic Acid (AA) and Smad3 inhibitor Naringenin (NG), AANG, effectively suppressed the progression of renal fibrosis in vivo." (PMID 36147472, 2022). "Erbb4-IR correlates negatively with SMAD7 expression and either inhibits or promotes TGF-β/Smad3-mediated renal fibrosis in vivo and in vitro." (PMID 34059951, 2021). "By contrast, the function of Smad2 and Smad7 is protective, which negatively regulates the TGF-β/Smad3 signaling in renal fibrosis and inflammation." (PMID 34054586, 2021). "Moreover, Erbb4-IR may also bind with Smad7 to promote renal fibrosis." (PMID 33574750, 2020). "For instance, studies have demonstrated that TGF-β/Smad3 promotes renal fibrosis by inducing the expression of miR-21, miR-433, and miR-192, which in turn suppressed PTEN, Smad7, ZEB1/2, and AZIN1, respectively." (PMID 32587662, 2020). "The experimental observations suggested that CA can inhibit Cd-provoked renal fibrosis by inhibiting TGF-β1/Smad signalling through blocking TGF-βR2–TGF-β1 interaction, preventing TGF-β1 activation by free radicals, and activating Smad7 expression." (PMID 31752142, 2019).
renal fibrosis (continued). "In that study, adenoviral vectors designed for expression of Smad7, which is an antagonist of TGF-β1–Smad signaling, were injected into the pelvic space of a rat model of renal fibrosis induced by UUO." (PMID 30410705, 2017). "As the consequence of intact Smad7, activation of both TGF-β/Smad3 signaling and NF-κB signaling in the diabetic kidney was inhibited, thereby resulting in attenuation of renal fibrosis and inflammation." (PMID 26807792, 2016). "The indices of renal fibrosis, the phosphorylation of Smad3, and the expression of alpha-smooth muscle actin (α-SMA), fibronectin, collagen III (Col III), E-cadherin, TGF-β, and Smad7 in response to DXR were all similarly modified by DAL." (PMID 28100935, 2016). "In summary, miR-21 contributes to renal fibrosis through multiple alterations in cell metabolism, the regulation of signaling pathways, like Akt and/or ERK/MAPK pathways and targeting Smad7 protein, a negative regulator of TGF-β1/Smad3 signaling." (PMID 27610006, 2016). "Thus, the combination of AA and NG produces an additive effect on inhibition of renal fibrosis by inhibiting Smad3 while upregulating Smad7 and may represent as a novel and effective therapy for chronic kidney disease including diabetic and hypertensive nephropathy." (PMID 26474462, 2015). "In the context of renal fibrosis, TGF-β1 acts by stimulating Smad3 to mediate fibrosis, which is negatively regulated by Smad7." (PMID 25883225, 2015). "The functional importance of Smad7 in chronic AAN was demonstrated by the findings that deletion of Smad7 aggravated but restoration of Smad7 locally in the kidneys of Smad7 KO mice prevented AA-induced, TGF-β/Smad3-mediated progressive renal fibrosis." (PMID 25883225, 2015). "We found that AA, a triterpene from Centella Asiatica, functioned as a Smad7 agonist and suppressed TGF-β/Smad3-mediated renal fibrosis by inducing Smad7." (PMID 26474462, 2015). "In addition, inhibition of TGF-β/Smad3-mediated renal fibrosis by overexpressing renal Smad7 in the established chronic AAN further supported the inhibitory role of Smad7 in progressive chronic AAN and may also well explain the therapeutic effect of Smad7 on chronic AAN." (PMID 25883225, 2015). "Of these, Smad7 is an important regulator which operates via direct and indirect mechanism to suppress ANG II-mediated renal fibrosis and inflammation." (PMID 23301086, 2013). "In a rat nephrectomy model, overexpression of Smad7 blocked TGF-β/Smad signaling, and thereby inhibited miR-192 expression and renal fibrosis, suggesting that miR-192 may be an important downstream of the TGF-β/Smad3 signaling pathway." (PMID 37170506, 2023). "Our findings reveal the role of SETD2‐mediated H3K36me3 of Smad7 in regulating the TGF‐β/Smad signalling pathway in renal fibrogenesis and provide an innovative insight into SETD2 as a potential therapeutic target for the treatment of renal fibrosis." (PMID 37933774, 2023). "In conclusion, we identify a safe dosage and optimal combination ratio of AANG for preventive treatment of T2D and T2DN by effectively rebalancing Smad3/Smad7 signaling, thereby inhibiting TGF-β/Smad3-mediated renal fibrosis and NF-κB-driven renal inflammation." (PMID 36147472, 2022). "In addition, Erbb4-IR can also target Smad7, and specific silencing of Erbb4-IR expression up-regulates Smad7 in the kidneys, thereby attenuating TGF-β1/Smad3-induced renal fibrosis in vivo and in vitro." (PMID 36299256, 2022). "Focusing on the role of TGF-β1 expression in renal fibrosis, it was proved that UCG downregulated the protein expressions of TGF-β1, TGF-β receptor I, receptor II and Smad2/3, and upregulated the protein expressions of SnoN and Smad7." (PMID 35924053, 2022). "For instance, miR-21 accelerated renal fibrosis in DN by targeting PTEN and SMAD7." (PMID 35969018, 2022).